MRGPRX2 (MAS related GPR family member X2)
Diseases named in the same sentence as MRGPRX2 in open-access papers (continued):
Sharing a sentence is not in itself a finding about the gene and the disease.
anaphylaxis (continued). "This makes clarification of the role of MRGPRX2 in drug-induced anaphylaxis of particular importance." (PMID 34867939, 2021). "To this point, we have focused attention towards considering if and how MRGPRX2 contributes to drug-induced acute anaphylaxis." (PMID 34867939, 2021). "A recent study has compared blood-derived mast cells from patients who had likely IgE-dependent with a possible MRGPRX2-dependent drug-induced anaphylaxis." (PMID 34867939, 2021). "Mast cell models derived from patients who suffered acute drug-induced anaphylaxis would be a highly valuable tool to identify if elevated MRGPRX2 expression or function underpin the drug hypersensitivity." (PMID 34867939, 2021). "Here we examine recent mechanistic advances in the understanding of drug-induced anaphylaxis in humans, with a focus on the critical role played by mast cell activation and the role of the Mas-related G protein-coupled receptor X2 (MRGPRX2)." (PMID 34867939, 2021). "Conclusive evidence that MRGPRX2 activation is a primary mechanism in drug-induced anaphylaxis continues to be a clinical challenge." (PMID 34867939, 2021). "Throughout, the key value in developing better clinical stratification of patients experiencing drug-induced anaphylaxis, to highlight those likely to have a MRGPRX2 basis, has also been emphasised." (PMID 34867939, 2021). "To date, there is no means of unambiguously attributing a clinical event of drug-induced acute anaphylaxis to MRGPRX2 activation." (PMID 34867939, 2021). "This reinforces the necessity of better understanding the role of MRGPRX2 in drug-induced anaphylaxis to determine if this receptor plausibly explains events where a clear connection to IgE sensitization cannot be made." (PMID 34867939, 2021). "As such, defining the true clinical role of MRGPRX2 in drug-induced anaphylaxis has wide-sweeping importance." (PMID 34867939, 2021). "Whilst these studies used existing iPSC lines, they support the generation of patient-specific mast cells from those who experienced possible MRGPRX2-dependent, acute-drug-induced anaphylaxis." (PMID 34867939, 2021). "The mast cells of patients with IgE-independent anaphylaxis to rocuronium were similar, in their MRGPRX2 expression and function, to those of patients with IgE-mediated anaphylaxis." (PMID 34385999, 2021). "Whilst this study focused exclusively on clinical samples from likely IgE-dependent Hymenoptera sting-induced anaphylaxis, a deficiency in PGE2 levels would also be predicted to potentiate MRGPRX2 agonist-induced mast cell activation." (PMID 34867939, 2021). "Recent studies found that elevated MRGPRX2 levels are associated with an increased risk of severe reactions, and MRGPRX2 may be a biomarker for predicting ICM-induced anaphylaxis." (PMID 40400633, 2025). "MCs are key players in anaphylaxis owing to their capacity to release histamine and other vasoactive mediators following allergen provocation or via IgE-independent triggers such as anaphylatoxins and Mas-related G-protein coupled receptor member X2 (MRGPRX2)." (PMID 40707759, 2025). "While clinical features of MRGPRX2-mediated reactions can mimic IgE-mediated anaphylaxis, certain features may favor the former—such as reactions occurring on first exposure, the need for higher doses to trigger symptoms, and shorter symptom duration." (PMID 41174719, 2025). "Instead, we present the possibility that the response could be mediated through Mas-related G protein-coupled receptor X2 (MRGPRX2), a divergent pathway leading to comparatively milder symptoms of anaphylaxis." (PMID 37664335, 2023). "These reagents could be utilized in the future to determine the role of MRGPRX2 in systemic anaphylaxis, including food allergy." (PMID 37063868, 2023).
anaphylaxis (continued). "Second, it is quite likely that for MRGPRX2 interactions with small ligands to lead to anaphylaxis, multiple mechanisms might be at play (e.g. genetic variations and other ecological perturbation such as modification of dosing and infusion time)." (PMID 36341461, 2022). "In conclusion, the expression of FcεRI on MCs, but not the quantitative expression of MRGPRX2 or the phenotype and function of basophil, plays a crucial role in determining the risk of wasp venom anaphylaxis in patients with non-advanced CMCD." (PMID 35281031, 2022). "For example, the MRGPRX2-mediated pathway was hypothesized in a patient with ISM who developed anaphylaxis to ciprofloxacin." (PMID 35958589, 2022). "Given the strong expression of MRGPRX2 in skin mast cells, it might be expected that cutaneous symptoms would be overt in putative MRGPRX2-dependent anaphylaxis." (PMID 34867939, 2021). "From a patient perspective, defining the role of MRGPRX2 is important as if confirmed, it may provide predictive, preventative and therapeutic strategies for drug-induced anaphylaxis." (PMID 34867939, 2021). "A question that is raised repeatedly in the literature is whether MRGPRX2 activation is capable of triggering anaphylaxis." (PMID 34421893, 2021). "This arrests MRGPRX2/PLC-γ1/IP3R signal transduction, thereby attenuating anaphylactoid reactions, including anaphylactic shock." (PMID 40918407, 2025). "As of today, many questions on the role of MRGPRX2 in NMBA- and FQ-induced anaphylaxis remain unanswered and need to be addressed." (PMID 34385999, 2021). "Hymenoptera and drug induced anaphylaxis in patients with negative skin testing has now been attributed to altered or increased expression of mast cells MRGPRX2." (PMID 39585499, 2024). "This again reinforces the lack of clarity in the role that MRGPRX2 expression plays clinically in drug-induced anaphylaxis even in mast cell disease." (PMID 34867939, 2021). "There is, currently, no validated assay to test patients for MRGPRX2-dependent anaphylaxis." (PMID 34385999, 2021).
atopic dermatitis (22 papers, 2019 to 2025). "Activation of MRGPRX2/B2 by the neuropeptide substance P (SP) is implicated in neurogenic inflammation, chronic urticaria, mastocytosis and atopic dermatitis." (PMID 35126366, 2021). "Moreover, MRGPRX2-mediated MC activation is implicated in multiple dermatoses, e.g., chronic spontaneous urticaria and atopic dermatitis." (PMID 37404822, 2023). "Activation of MCs through MRGPRX2 and the subsequent release of tryptase has been shown to be linked to non-histaminergic pruritus, most likely via activation of protease activated receptor 2 expressed by sensory nerves, as observed in atopic dermatitis-related pruritus." (PMID 39068637, 2024). "Furthermore, MRGPRX2 has recently been implicated in the pathogenesis of mastocytosis, neurogenic inflammation, chronic urticaria, chronic prurigo, rosacea, atopic dermatitis, and allergic contact dermatitis/itch." (PMID 36275683, 2022). "The authors provide several arguments for the important role of MRGPRX2 in chronic spontaneous urticaria, atopic dermatitis, rosacea, psoriasis, chronic pruritus, and chronic prurigo." (PMID 39996342, 2025). "MRGPRX2 is an important target for mediating the pathogenesis of a variety of diseases, including atopic dermatitis, chronic spontaneous urticaria, pseudoallergic reactions, hypersensitivity‐type inflammation, and rosacea." (PMID 40901656, 2025). "Although most of the data on MRGPRX2 comes from in vitro studies, there are also ongoing clinical trials using agonist of this receptor in chronic spontaneous urticaria and atopic dermatitis." (PMID 38812508, 2024). "Among the MRGPRX receptors, MRGPRX2 is a crucial mast cell receptor involved in anaphylactoid drug reactions and various skin and mucosal disorders, such as urticaria, atopic dermatitis, rosacea, and allergic rhinitis." (PMID 38689089, 2024). "The influence of Celastrol on atopic dermatitis was remarkably reversed by overexpression of MRGPRX2." (PMID 36712922, 2023). "A previous study indicated that MRGPRX2-mediated mast cell activation contributed to local inflammation and sensory neuron excitation in atopic dermatitis." (PMID 36712922, 2023). "Collectively, our finding suggests that RYR activation contributes to MRGPRX2-triggered pseudo-allergic dermatitis, and provides a potential approach for MRGPRX2-mediated disorders." (PMID 37404822, 2023). "Firstly, the influence of Celastrol on atopic dermatitis through the MRGPRX2/ORAI axis needs to be validated with human atopic dermatitis tissues." (PMID 36712922, 2023). "Other publications related with the roles of MRGPRX2-mediated mast cells in atopic dermatitis are mainly reviews." (PMID 36712922, 2023). "The role of MRGPRX2 is insinuated in the pathogenesis of urticaria, atopic dermatitis, and psoriasis." (PMID 37404822, 2023). "This raises the interesting possibility that unlike IgE-mediated PCA and itch, GRK2 provides an inhibitory signal for atopic dermatitis through MRGPRX2/B2 desensitization." (PMID 37063868, 2023). "Celastrol greatly inhibited atopic dermatitis-related tissues injury, mast cell production, histamine release, scratching level, inflammatory factor expression, and activation of MRGPRX2/ORAI axis in the DNFB-induced atopic dermatitis model." (PMID 36712922, 2023). "Mrgprb2-KO mice have been reported to have significantly reduced inflammation, including itching in various models of allergic contact dermatitis, suggesting that MRGPRX2 is involved in the development of ACD as well as atopic dermatitis." (PMID 34831128, 2021). "Taken together, these findings suggest that MRGPRX2/Mrgprb2 participate in neurogenic inflammation, chronic urticaria, atopic dermatitis, and pain." (PMID 31652731, 2019). "Topical formulations containing chitosan could be explored for localized conditions like atopic dermatitis or rosacea, leveraging its anti‐inflammatory and potentially barrier‐enhancing properties alongside MRGPRX2 inhibition." (PMID 40901656, 2025).
atopic dermatitis (continued). "Moreover, tryptase released by MRGPRX2/MRGPRB2 activation is also involved in the release of type 2 cytokines, which contributes to the inflammation associated with atopic dermatitis." (PMID 39493768, 2024). "We demonstrated that Celastrol could inhibit atopic dermatitis through suppressing MRGPRX2/ORAI axis." (PMID 36712922, 2023). "This study might provide a novel thought for the prevention and treatment of atopic dermatitis by regulating MRGPRX2." (PMID 36712922, 2023). "The purpose of this study is to explore whether the molecular mechanism of Celastrol intervention on mast cell degranulation in atopic dermatitis is related to the interaction of MRGPRX2/ORAI." (PMID 36712922, 2023). "In the present study, we demonstrated that Celastrol could greatly inhibit atopic dermatitis-related tissue injury, mast cell production, histamine release, scratching level, inflammatory factor expression, and activation of the MRGPRX2/ORAI axis in the DNFB-induced atopic dermatitis model." (PMID 36712922, 2023). "However, the regulatory role of Celastrol was remarkably reversed by overexpression of MRGPRX2, indicating that Celastrol might regulate atopic dermatitis through targeting MRGPRX2." (PMID 36712922, 2023). "In addition, ORAI channels contributed to MRGPRX2-mediated mast cell activation and the inactivation of mast cells might provide a novel treatment for neuropeptide substance P-induced atopic dermatitis." (PMID 36712922, 2023). "In addition, activation of MRGPRX2 by the neuropeptide substance P (SP) and the pro-adrenomedullin peptide (PAMP-12) is associated with a variety of cutaneous conditions such as neurogenic inflammation, pain, atopic dermatitis, urticaria, and itch." (PMID 36275683, 2022). "The neuropeptide substance P (SP) mediates neurogenic inflammation and pain and contributes to atopic dermatitis in mice through the activation of mast cells (MCs) via Mas-related G protein-coupled receptor (GPCR)-B2 (MrgprB2, human ortholog MRGPRX2)." (PMID 34070125, 2021). "Following successful basic in vivo studies in mouse and dog models, two clinical trials have been initiated with an orally administered specific MRGPRX2 antagonist—the synthetic small molecule compound EP262—in the indications of chronic spontaneous urticaria and atopic dermatitis." (PMID 38535499, 2024). "The development of high-affinity MRGPRX2 inhibitors is expected to make a significant contribution to the treatment of neurogenic inflammation, type 2 inflammation such as atopic dermatitis and chronic urticaria, and non-histaminic itch." (PMID 34831128, 2021). "In addition, mast cells in the skin express MRGPRX2, which mediates diseases, such as rosacea, atopic dermatitis, nonhistaminergic itch, and pseudoallergy and MRGPRX2 is involved in the majority of peptide stimulation-associated activation in human mast cells." (PMID 39144634, 2024). "However, whether Celastrol regulates atopic dermatitis through MRGPRX2 has not been reported." (PMID 36712922, 2023).
asthma (16 papers, 2018 to 2025). "Type 2 immune response in AD involves MrgprB2 activation in MCs by SP, and we have recently shown an increased level of MRGPRX2-expressing MCs is associated with severe asthma." (PMID 39483467, 2024). "We recently demonstrated that the number of MRGPRX2-positive MCs is significantly enhanced in the lungs of the patients who died from asthma compared to patients who died from unrelated causes." (PMID 39483467, 2024). "Nevertheless, the expression of MRGPRX2 on mast cells and the number of MRGPRX2+ mast cells are higher in lung biopsies from patients who died from asthma-related causes than in lung biopsies from patients who died from other causes." (PMID 31191511, 2019). "Thus, caution may have to be exercised when using these especially in patients who are pre-disposed to co-morbidities where MRGPRX2 is either upregulated (asthma, mastocytosis) or mutated." (PMID 36275707, 2022). "Although several studies report increased numbers of MRGPRX2-positive mast cells in lung tissue from patients with asthma, its exact role in the pathogenesis of asthma remains incompletely understood and difficult to explore." (PMID 41169391, 2025). "Immune cells recruitment and an antimicrobial role has been shown through MRGPRX2 and rhinovirus induced increase in beta defensins production in bronchial epithelial cells has been shown to activated MRGPRX2 and mediate asthma exacerbations." (PMID 39585499, 2024). "The identification of the CXCL14 receptor that is expressed on mast cells and other MRGPRX2-expressing cells and tissues will facilitate studying and investigating its role in inflammatory diseases such as fibrosis, asthma, arthritis, and skin diseases." (PMID 38184723, 2024). "Beyond the skin, MRGPRX2-expressing MCs are increased in the gingiva of patients with chronic periodontitis, and lung MCs of individuals who died from asthma." (PMID 36275683, 2022). "Mast cell MRGPRX2 plays a pivotal role in mediating pseudo-allergic reactions to several FDA approved drugs and chronic inflammation associated with asthma, urticaria, and rosacea." (PMID 32038646, 2019). "Given that mast cell MRGPRX2 plays a pivotal role in mediating pseudo-allergic reactions to several FDA-approved drugs and chronic inflammation associated with asthma, urticaria and rosacea, our studies provide a strong rationale for testing osthole as a novel treatment option for these conditions." (PMID 32391014, 2020). "To conclude, MRGPRX2-mediated activation of mast cells may contribute to the pathogenesis of asthma." (PMID 31191511, 2019). "The activation of MRGPRX2 may also be related with exacerbations of asthma symptoms that occur in connection with viral respiratory infections." (PMID 31191511, 2019). "Thus, MRGPRX2 may contribute to mast cell–mediated airway responses under certain conditions, but its precise role in asthma pathogenesis requires further clarification." (PMID 41169391, 2025). "Besides, recent studies found that serum MRGPRX2 levels were significantly elevated in asthma patients, and it could serve as a biomarker for predicting treatment outcomes." (PMID 35733520, 2022). "Moreover, a previous study demonstrated that MRGPRX2-mediated activation of mast cells may contribute to the pathogenesis of asthma." (PMID 35733520, 2022). "As a result, MRGPRX2 is responsible for mediating mast cell anaphylactic and pseudo-allergic reactions to several US Food and Drug Administration (FDA)-approved drugs and has been implicated in the pathology of chronic inflammatory diseases such as asthma, rosacea, and urticaria." (PMID 32391014, 2020). "Thus, development of selective MRGPRX2 antagonists could serve as novel target for the modulation of asthma." (PMID 29295703, 2018).
asthma (continued). "For instance, anti-allergic asthma lead compounds were explored through Mas-related G protein-coupled receptor-X2 (MrgX2) CMC, targeting the mast cell MRGPRX2; natural products, such as diamine, shikotin and acetylshikotin, exhibited promising effects on asthma." (PMID 38956679, 2024). "We detected low level of MRGPRX2 in non-asthma lung MCs but its expression was significantly upregulated in asthma lung MCs." (PMID 29295703, 2018).
urticaria (16 papers, 2019 to 2025). A vascular reaction of the skin characterized by erythema and wheal formation due to localized increase of vascular permeability. "The activation of the multifaceted MRGPRX2 has been described in pseudoallergy and urticaria and very recently was suspected as a missing link between Hist‐AE and C1‐INH‐HAE." (PMID 40685762, 2025). "Among them, MRGPRX2 is a prominent receptor responsible for FcεRI-independent allergic reactions, including itch, rosacea, urticaria and adverse drug reactions." (PMID 39148726, 2024). "Regarding CIU, it was reported that urticaria patients are characterized by overexpression of MRGPRX2, while a newer publication confirmed this by also showing enhanced skin reactivity of patients to MRGPRX2 drug ligands." (PMID 33429916, 2021). "Thus, this study should be considered a foundation for future projects focussing on MRGPRX2 signalling and the sensitivity profile of basophils in urticaria patients." (PMID 37275407, 2023). "MRGPRX2 is a member of the Mas-related gene receptor family and it is emerging as a prominent receptor involved in non-IgE-mediated allergic reactions, including urticaria, rosacea, itch, atopic dermatitis and adverse drug reactions." (PMID 39148726, 2024).